RNU6-808P (RNA, U6 small nuclear 808, pseudogene)
Gene: Small nuclear RNA gene on chromosome 12 (95,290,692 to 95,290,799, forward strand). Ensembl gene ENSG00000212535.
Homologues: Orthologues: chimpanzee U6 (100% identical), macaque U6 (95% identical), dog U6 (78% identical), dog U6 (65% identical), guinea pig U6 (65% identical). Paralogues in human: RNU6-259P (81% identical), RNU6-393P (81% identical), RNU6-792P (81% identical), RNU6-1181P (81% identical), RNU6-45P (81% identical), RNU6-1024P (80% identical), RNU6-10P (80% identical), RNU6-1145P (80% identical), RNU6-151P (80% identical), RNU6-338P (80% identical), RNU6-41P (80% identical), RNU6-562P (80% identical), and 1285 more.